ANO8 (anoctamin 8)
Description:
Does not exhibit calcium-activated chloride channel (CaCC) activity.
Synonyms: KIAA1623; TMEM16H
Tractability: Antibody: UniProt places it where antibodies can reach, with high confidence; its Gene Ontology location is reachable by antibodies, with high confidence; UniProt predicts a signal peptide or a membrane-spanning region. PROTAC: its protein half-life has been measured.
Gene: Protein-coding gene on chromosome 19 (17,323,223 to 17,334,855, reverse strand). Ensembl gene ENSG00000074855.
Subcellular location: Cell membrane
Pathways (Reactome):
Metabolism of proteins: Post-translational protein phosphorylation; Regulation of Insulin-like Growth Factor (IGF) transport and uptake by Insulin-like Growth Factor Binding Proteins (IGFBPs)
Disease: Induction of Cell-Cell Fusion
Transport of small molecules: Stimuli-sensing channels
Gene Ontology:
Molecular function: intracellularly calcium-gated chloride channel activity; chloride channel activity
Biological process: chloride transmembrane transport; monoatomic ion transmembrane transport
Cellular component: plasma membrane; endoplasmic reticulum lumen
Genetic constraint (gnomAD): Loss-of-function variants: 67 observed, 103.3 expected, observed/expected ratio (o/e) 0.65, 90% interval 0.53 to 0.8. The upper end of that interval is the gene's LOEUF score, 0.8, which puts it in group 3 of 6, group 1 being the genes least tolerant of losing a copy. Missense variants: 1,433 observed, 1,502.5 expected, observed/expected ratio (o/e) 0.95, 90% interval 0.91 to 1. Synonymous variants: 679 observed, 635.78 expected, observed/expected ratio (o/e) 1.07, 90% interval 1 to 1.14.
Homologues: Orthologues: chimpanzee ANO8 (100% identical), macaque ANO8 (99% identical), pig ANO8 (94% identical), dog ANO8 (93% identical), mouse Ano8 (75% identical), rat Ano8 (75% identical), guinea pig ANO8 (74% identical), tropical clawed frog ano8 (57% identical), zebrafish ano8b (56% identical), zebrafish ano8a (47% identical), Drosophila melanogaster wwk (31% identical), Caenorhabditis elegans anoh-2 (26% identical). Paralogues in human: ANO3 (16% identical), ANO5 (16% identical), ANO4 (16% identical), ANO6 (16% identical), ANO10 (16% identical), ANO2 (16% identical), ANO1 (15% identical), ANO7 (15% identical), ANO9 (13% identical), PPP1R7 (6% identical).
Diseases named in the same sentence as ANO8 in open-access papers:
ANO8 is named in the same sentence as 7 diseases in open-access papers, as found by Europe PMC text mining. Sharing a sentence is not in itself a finding about the gene and the disease. The quoted sentences say what the papers report.
autism (1 paper, 2026). Persistent deficits in social interaction and communication and interaction as well as a markedly restricted repertoire of activity and interest as well as repetitive patterns of behavior. "Around 50% and around 30% of the association signal, for MAP1A and for ANO8, respectively, was driven by rare deleterious variants in individuals diagnosed with ADHD only (without comorbid schizophrenia, ID or autism), whereas the ANK2 signal was driven mainly by ADHD with co-occurring autism or ID." (PMID 41224997, 2026).
cholestasis (1 paper, 2020). Impairment of the bile flow caused by obstruction within the liver, or outside the liver in the bile duct system. "Of course, it is noteworthy that the role of the ANO8 gene and its mutations in cholestasis of pregnancy is based on bioinformatics analysis derived from WES data and network data." (PMID 32942997, 2020).
prostate carcinoma (1 paper, 2024). A carcinoma that arises from epithelial cells of the prostate gland. "One of the key observations made in our analysis was much lower expression of ANO1, ANO8 and ANO10 in LNCap low-metastatic and DU145 moderately-metastatic cells when compared to PC3 highly-metastatic prostate cancer cells." (PMID 38773164, 2024). "Also, considering that DNA methylation mainly affects gene expression at the level of transcription, it was reasonable to speculate that transcription is the primary process through which the expression of ANO1, ANO8, and ANO10 is regulated in LNCaP, DU145, and PC3 prostate cancers." (PMID 38773164, 2024).
cancer (1 paper, 2020). A tumor composed of atypical neoplastic, often pleomorphic cells that invade other tissues. "Anoctamin 8 (ANO8) is associated with a human disorder that is often overexpressed in diverse cancers." (PMID 32792959, 2020).
ANO8 also shares sentences with these, for which no sentence is quoted: breast carcinoma (2 papers); intrahepatic cholestasis (1); schizophrenia (1).